HDAC6 (histone deacetylase 6)
Diseases named in the same sentence as HDAC6 in open-access papers (continued):
Sharing a sentence is not in itself a finding about the gene and the disease.
Hyperglycemia (6 papers, 2016 to 2025). An increased concentration of glucose in the blood. "Tubastatin A, an isoform-selective HDAC6 inhibitor, can mitigate hyperglycemia-provoked cardiac dysfunction, cardiac infarction, and free radical generation by facilitating the Prdx1 acetylation." (PMID 34071497, 2021). "We then measured the expression and retinal tissue distribution of HDAC6 in STZ-rats (8 weeks of hyperglycemia) compared to normoglycemic age-matched control rats." (PMID 32660051, 2020). "In summary, our data implicate HDAC6 activation in mediating hyperglycemia-induced retinal oxidative/nitrative stress leading to retinal microangiopathy and, potentially, DR." (PMID 32660051, 2020). "Western blotting analysis showed a 2.2-fold increase of HDAC6 protein levels in retinas of STZ-rats at 8 weeks of hyperglycemia in comparison to age-matched normoglycemic control rats (p < 0.006; n = 6)." (PMID 32660051, 2020). "Selective inhibition of HDAC6 activity protected kidneys from hyperglycaemia in db/db mice." (PMID 32885602, 2020). "To understand the potential role of HDAC6 in this process, we investigated TS effects on hyperglycemia-induced oxidative/nitrative stress by measuring retinal levels of superoxide, by dihydroethidium (DHE) staining and nitrotyrosine (NT) and 4-hydroxynonenal (4-HNE) by dot-blot analysis." (PMID 32660051, 2020). "Furthermore, HDAC6 activation has been demonstrated to modulate hyperglycemia-induced oxidative stress in the retina, which can result in retinal microangiopathy and may even precipitate DR." (PMID 40469433, 2025). "GLP-1 treatment has been reported to alleviate diabetic retinopathy by inhibiting hyperglycemia-provoked autophagy in the retina of T2D rats mediated through the restoration of GLP-1R expression and HDAC6 inhibition." (PMID 34071497, 2021). "Although the precise mechanisms by which hyperglycemia induces HDAC6 activity in myocardium are not fully understood, evidence supports a vital role for HDAC6 in the stress response." (PMID 30046381, 2018).
Insulin resistance (6 papers, 2020 to 2025). Increased resistance towards insulin, that is, diminished effectiveness of insulin in reducing blood glucose levels. "We found insulin resistance to be associated with PD and HDAC6 may play an important role in this process." (PMID 32205467, 2020). "HDAC6 can promote insulin resistance by deacetylating phosphatase and tensin homolog (PTEN) in ovarian OVCAR-3 cells, and PTEN has in turn been shown to be involved in the pathophysiology of PD." (PMID 32205467, 2020). "We highlight the non-preserved module in PD associated with insulin resistance, and the hub HDAC6 identified in this module." (PMID 32205467, 2020). "We highlighted that the PD module not preserved in HCs was associated with insulin resistance, and HDAC6 was identified as a hub gene in this module which may have the role of influencing tau phosphorylation and autophagic flux in neurodegenerative disease." (PMID 32205467, 2020). "Kumar and Datta in 2022 demonstrated that the upregulation of H19 in skeletal muscles in mice promoted insulin resistance in type 2 diabetes via increased IRS1 and downregulated HDAC6 expression." (PMID 40176927, 2024). "We show that H19 regulates the levels of HDAC6 within the cell and this regulation consequently determines IRS1 levels and insulin resistance in the skeletal muscle." (PMID 35842608, 2022). "Furthermore, it has been reported that deacetylation of histone H3 lysine 9 (H3K9) via histone deacetylase 6 (HDAC6) leads to suppression of insulin receptor substrate 2 (IRS2) protein, which in turn contributes to the development of insulin resistance." (PMID 40408591, 2025). "Previous studies showed that HDAC6 and HDAC8 promoted insulin resistance in animal models." (PMID 36118901, 2022).
chronic obstructive pulmonary disease (5 papers, 2015 to 2025). A chronic and progressive lung disorder characterized by the loss of elasticity of the bronchial tree and the air sacs, destruction of the air sacs wall, thickening of the bronchial wall, and mucous accumulation in the bronchial tree. "In addition, HDAC6-mediated autophagic turnover of ciliary proteins has recently been reported to be associated with ciliary dysfunction in the chronic obstructive pulmonary disease model." (PMID 26246421, 2015). "HDAC6 is an essential autophagy effector, reported to participate in regulation of autophagy-related cilia dysfunction during chronic obstructive pulmonary disease." (PMID 27888631, 2016).
frontotemporal dementia (5 papers, 2011 to 2024). Frontotemporal dementia (FTD) comprises a group of neurodegenerative disorders, characterized by progressive changes in behavior, executive dysfunction and language impairment, as a result of degeneration of the medial prefrontal and frontoinsular cortices. "In conjunction with another gene product (valosin-containing protein) associated with a form of FTD (inclusion body myopathy with Paget disease of bone and frontotemporal dementia) and ALS, HDAC6 decides over proteasomal versus autophagic breakdown fates." (PMID 21878116, 2011).
head and neck cancer (5 papers, 2015 to 2025). A primary or metastatic malignant neoplasm affecting the head and neck. "We next examined HDAC1, HDAC2 and HDAC6 levels in 8 head and neck cancer cell lines and normal human oral keratinocytes (HOK)." (PMID 26000099, 2015). "We measured HDAC1, HDAC2 and HDAC6 levels in 20 frozen tissue samples from head and neck cancer patients (10 tumor and 10 adjacent normal controls) by real-time PCR." (PMID 26000099, 2015). "Simultaneously inhibiting HDAC6 and BET, which potentially drive tumors to advanced stages, could be a promising strategy to treat head and neck cancer." (PMID 32961679, 2020). "HDAC6 and SP1 interaction has neither been demonstrated in head and neck cancers nor radiation resistant cancers." (PMID 39800760, 2025).
lupus nephritis (5 papers, 2019 to 2024). Glomerulonephritis in the context of systemic lupus erythematosus. "An HDAC6 inhibitor was previously shown to greatly reduce lupus nephritis in mice." (PMID 36750564, 2023). "Moreover, HDAC6 plays an active role in lupus nephritis, treatment with a novel HDAC6-selective inhibitor CKD-506 can improve renal outcomes." (PMID 33896334, 2021). "In lupus nephritis(LN), the researchers treated NZB/W lupus mice with a selective histone deacetylase 6 (HDAC6) inhibitor for 4 weeks and showed that HDAC6 inhibition decreased B-cell activating signaling pathways, resulting in a significant reduction in LN symptoms." (PMID 35251009, 2022). "A serial analysis of gene expression (SAGE) data for HDAC6 suggests that HDAC6 is minimally express in normal kidney tissues, however, the level of HDAC6 expression is up-regulated in various kidney diseases, such as autosomal dominant polycystic kidney disease (ADPKD), lupus nephritis, and AKI." (PMID 33896334, 2021). "ACY-738 treatment of mice increased a total of 5 canonical pathways, and none were significantly decreased in human SLE although glutathione mediated detoxification (Z = 3.5 in HDAC6 inhibitor treated mice) had negative Z scores for human lupus skin (−1.8) and lupus nephritis (−1.6)." (PMID 31708928, 2019).
medulloblastoma (5 papers, 2013 to 2019). A malignant, invasive embryonal neoplasm arising from the cerebellum. "This suggested that HDAC6 and tubulin acetylation are developmentally regulated and that HDAC6 dysregulation could be associated with medulloblastoma pathogenesis." (PMID 23951168, 2013). "In addition to HDAC1/2, the class II protein HDAC6 is found upregulated in medulloblastoma tumors, and its inhibition shows tumor suppressive effects in preclinical models of Shh-medulloblastoma." (PMID 31244888, 2019). "However, it remains to be determined whether increased HDAC6 activity contributes to medulloblastoma pathogenesis in ways other than proliferation, eg tumor cell commitment or tumor metastasis." (PMID 23951168, 2013). "At this point, it is not known whether abnormal HDAC6 expression and activity contributes to medulloblastoma progression overall, or possibly during a specific time window in early or post-natal cerebellum development." (PMID 23951168, 2013).
memory impairment (5 papers, 2013 to 2023). "Several researchers showed that reduction or inhibition of HDAC6 ameliorated memory impairment in AD mice model." (PMID 28241840, 2017). "In conclusion, our study shows that reducing endogenous HDAC6 levels ameliorates memory impairment in a mouse model for neurodegeneration." (PMID 23184605, 2013). "While our data provides genetic evidence that reducing endogenous HDAC6 levels protects against memory impairment in an AD mouse model, it remains to be tested whether pharmacological inhibition of HDAC6 would have similar effects." (PMID 23184605, 2013). "Therefore, HDAC6 inhibitor could recover memory impairment in AD mice models." (PMID 28241840, 2017).
migraine (5 papers, 2021 to 2025). "The study of JNK/c-Jun cascade as a future target for migraine therapy, as well as the study of HDAC6 inhibitors as potential drugs for migraine treatment, can be considered very promising, which underlines the need for more studies regarding the role of histone acetylation in migraine." (PMID 37298078, 2023). "The human migraine trigger, nitroglycerin, produced chronic migraine-associated pain and decreased neurite growth in headache-processing regions, which were reversed by HDAC6 inhibition." (PMID 33856345, 2021). "Thus, HDAC6 is expressed and regulated dynamically in regions that are critical for migraine-associated pain processing." (PMID 33856345, 2021). "Conversely, CGRP can change the epigenetic profile of neuronal and glial cells as shown for its involvement in epigenetic regulation of neural cytoarchitecture changes related to migraine chronification mediated by histone deacetylase 6 (HDAC6)." (PMID 37199585, 2023). "We use validated mouse models of migraine to show that HDAC6-inhibition is a promising migraine treatment and reveal an undiscovered cytoarchitectural basis for migraine chronicity." (PMID 33856345, 2021). "Reduction in neuronal complexity was also observed in this model of migraine aura, and again HDAC6 inhibition restored neuronal plasticity and decreased the number of CSD events." (PMID 33856345, 2021). "Cortical spreading depression (CSD), a physiological correlate of migraine aura, also decreased cortical neurite growth, while HDAC6-inhibitor restored neuronal complexity and decreased CSD." (PMID 33856345, 2021). "Again, we observed decreased neuronal complexity in migraine related sites, which was reversed by a HDAC6 inhibitor." (PMID 33856345, 2021). "Pretreatment with ACY-738 resulted in significantly fewer CSD events relative to vehicle controls, indicating that HDAC6 inhibition is also effective in this mechanistically separate migraine model." (PMID 33856345, 2021). "We chose to focus on the role of HDAC6 in tubulin acetylation and microtubule dynamics, as we observed changes in neuronal complexity in migraine models." (PMID 33856345, 2021). "Incidentally, CGRP may be involved in neural changes under the modulation operated by HDAC6, which may be related to migraine." (PMID 40711166, 2025). "In summary, CGRP may be involved in epigenetically regulated changes in neural cytoarchitecture that may be related to migraine and HDAC6 may control this process." (PMID 35682830, 2022). "Future studies will explore the contribution of these other mechanisms by which HDAC6 may impact neuronal complexity in migraine." (PMID 33856345, 2021). "The aims of this study were to determine if altered neuronal cytoarchitecture facilitates the chronic migraine state and whether modifying this by inhibition of HDAC6 would be effective in mouse models of migraine." (PMID 33856345, 2021). "Our results suggest that HDAC6 inhibitors may restore cellular adaptations induced by chronic disease states but may not otherwise affect healthy physiological function; and such compounds could contribute to the migraine therapeutic armamentarium." (PMID 33856345, 2021). "CGRP may be involved in changes in neural cytoarchitecture that are controlled by histone deacetylase 6 (HDAC6) and can be related to migraine." (PMID 35682830, 2022).
osteoarthritis (5 papers, 2016 to 2025). A noninflammatory degenerative joint disease occurring chiefly in older persons, characterized by degeneration of the articular cartilage, hypertrophy of bone at the margins and changes in the synovial membrane. "ACY-1215 is recognized as a selective HDAC6 inhibitor, noted for its chondroprotective properties in osteoarthritis (OA), although its impact on subchondral bone has yet to be elucidated." (PMID 39857301, 2025). "Using conventional molecular biology methods, our results showed that the level of HDAC6 increases both in the cartilage of osteoarthritis (OA) mice and TBHP-treated chondrocytes in vitro." (PMID 33744850, 2021). "Notably, the upregulation of HDAC6 expression in osteoblasts has been shown to promote osteoarthritis (OA) progression, suggesting that HDAC6 inhibitors hold promise as potential therapeutic agents for OA." (PMID 39857301, 2025). "Collectively, by performing conventional molecular methods, our results revealed that treatment with TubA significantly ameliorates osteoarthritis and inhibits the level of HDAC6 in chondrocytes, which results in activation of autophagy, cell survival and reduction of ECM degradation." (PMID 33744850, 2021). "Several chromatin modifying enzymes such as HAT1, KAT5, HDAC6, MBD1, and DNMT3A were downregulated at gene expression level in women with post-menopausal osteoporosis and osteoarthritis, with superior quantity and quality of bone being directly associated with HAT1, HDAC6, and MBD1 expression." (PMID 33805567, 2021).
proteinopathies (5 papers, 2020 to 2024). "Histone deacetylase 6 (HDAC6) is an emerging target for the treatment and diagnosis of proteinopathies." (PMID 38831171, 2024). "Overall, our study suggests that the UBP ZnF domain of HDAC6 performs various regulatory functions apart from its classical function in aggresome formation in protein misfolding diseases." (PMID 33933071, 2021). "Overall, our study suggests that ZnF domain of HDAC6 performs various regulatory functions apart from its classical function in aggresome formation in protein misfolding diseases." (PMID 33933071, 2021). "In line with these considerations, expression levels of HDAC6 increases sharply in protein misfolding diseases." (PMID 33933071, 2021). "Taken together, we concluded that overexpression of HDAC6 attenuates UPS impairment in TDP-43/ATXN2 flies, which is similar to what was found in the cell-based TDP-43 proteinopathy model." (PMID 33282865, 2020). "Importantly, HDAC6 overexpression represses the accumulation of ubiquitinated aggregates in cell models and Drosophila models of TDP-43 proteinopathy." (PMID 33282865, 2020). "Thus, the reactivation of microtubule functions through HDAC6 inhibition might reverse not only defects in microtubule-dependent transport, but also the accumulation of TDP-43 aggregates, providing a potential therapeutic approach for the TDP-43 proteinopathies, including ALS/FTD." (PMID 38311779, 2024).
spinobulbar muscular atrophy (5 papers, 2011 to 2021). "Compensatory autophagy was induced in response to a dysfunctional UPS in a Drosophila model of the spinobulbar muscular atrophy via a histone deacetylase 6 (HDAC6)-dependent aggresome pathway." (PMID 34751669, 2021). "For example, increased expression of histone deacetylase (HDAC6) reduces degeneration in flies with genetic inhibition of the UPS and in a fly model of spinobulbar muscular atrophy; the effect of HDAC6 is mediated by an increase in autophagy." (PMID 25062253, 2014). "A Drosophila model in which TDP-43 is silenced shows decreased HDAC6 expression, and HDAC6 overexpression is able to rescue the phenotype of a Drosophila model of spinobulbar muscular atrophy." (PMID 23634874, 2013). "In contrast, HDAC5 or HDAC6 was unable to mediate rescue of the photoreceptors in the rd1 mice, despite the ability of HDAC6 to rescue neurodegeneration in a Drosophila model of spinobulbar muscular atrophy." (PMID 23289056, 2011). "In a fly model of spinobulbar muscular atrophy, macroautophagy compensates for impaired UPS function in a histone deacetylase 6 (HDAC6)-dependent manner." (PMID 25330936, 2015).
synucleinopathies (5 papers, 2020 to 2026). "The association between HDAC6 and the pathogenesis of α-Synucleinopathies emerged when histopathological analysis in brain sections from PD patients revealed highly concentrated expression of HDAC6 within LBs, suggesting a possible role of HDAC6 in the formation of such inclusions." (PMID 33041780, 2020). "Since phospho-HDAC6 is present in α-synuclein inclusion bodies of PD and also in the MSA patient, we asked whether phospho-HDAC6 could also be linked to protein aggregation in neurodegenerative diseases beyond synucleinopathies." (PMID 32655357, 2020). "HDAC6 (histone deacetylase 6) has been suggested to regulate the pathologies of synucleinopathies including PD, possibly by deacetylating HSP90 that regulates α-synuclein degradation by CMA." (PMID 39949604, 2025). "Whereas emerging evidence link HDAC6 to synucleinopathies, the impact of modulating its activity on neurodegeneration is still debated." (PMID 37569662, 2023). "In α-Synucleinopathies, HDAC6 co-localizes with α-Syn in LBs and GCIs from PD and MSA samples, respectively." (PMID 33041780, 2020). "The main goal of this review is to summarize and critically discuss previous in vitro and in vivo data regarding the specific role of HDAC6 in the context of α-Syn accumulation and protein aggregation in α-Synucleinopathies." (PMID 33041780, 2020). "To summarize, it becomes clear that HDAC6 is involved in the pathology of α-Synucleinopathies by interfering with the accumulation of α-Syn oligomers and the formation of protein aggregates." (PMID 33041780, 2020). "HDAC6 may represent an attractive target for the therapy of α-Synucleinopathies, however, the effects of its enzymatic (deacetylation activity) or non-enzymatic activity (binding to ubiquitin) on α-Syn inclusion formation are still not conclusive." (PMID 33041780, 2020). "Although there are substantial findings regarding the potential neuroprotective effects in the modulation of HDACs activity in α-Synucleinopathies, the focus on HDAC6 increased with the demonstration that HDAC6 plays an important role in the regulation of different protein degradation mechanisms." (PMID 33041780, 2020). "Thus, it appears that prolonged HDAC6 inhibition might be safely tolerated and HDAC6 inhibitors may have potential for the treatment of neurodegenerative tauopathies and α-synucleinopathies." (PMID 41330635, 2026). "Finally, understanding how the effects of HDAC6 on other basic cellular mechanisms may interfere with the vulnerability to α-Syn will be crucial in the future search for strategies to target HDAC6 for disease modification in α-Synucleinopathies." (PMID 33041780, 2020). "Therefore, further studies focused on the role of HDAC6 in α-Synucleinopathy models." (PMID 33041780, 2020). "We performed double immunofluorescence for α-synuclein and phospho-HDAC6 on one patient affected by MSA, a synucleinopathy characterized by the presence of α-synuclein aggregates mainly in oligodendrocytes." (PMID 32655357, 2020). "Despite the small cohort of patients used in this study, the presence of phosphorylated HDAC6 seems to be a common feature of intracellular inclusions in α-Synucleinopathies, while it was absent in β-amyloid plaques derived from AD brains." (PMID 33041780, 2020). "Whether HDAC6 and Sirtuin 2 may share common mechanisms of neuroprotection in α-Synucleinopathy is not completely clear." (PMID 33041780, 2020).